TFAP2D (transcription factor AP-2 delta)
Description:
Sequence-specific DNA-binding protein that interacts with inducible viral and cellular enhancer elements to regulate transcription of selected genes. AP-2 factors bind to the consensus sequence 5'-GCCNNNGGC-3' and activate genes involved in a large spectrum of important biological functions including proper eye, face, body wall, limb and neural tube development. They also suppress a number of genes including MCAM/MUC18, C/EBP alpha and MYC (By similarity).
Synonyms: TFAP2BL1; AP-2delta
Tractability: PROTAC: ubiquitination databases record sites on it.
Gene: Protein-coding gene on chromosome 6 (50,713,526 to 50,773,033, forward strand). Ensembl gene ENSG00000008197.
Subcellular location: Nucleus
Subcellular location (Human Protein Atlas): Nucleoplasm; Golgi apparatus; Vesicles
Pathways (Reactome):
Gene expression (Transcription): Activation of the TFAP2 (AP-2) family of transcription factors; Negative regulation of activity of TFAP2 (AP-2) family transcription factors
Gene Ontology:
Molecular function: protein binding; DNA-binding transcription activator activity, RNA polymerase II-specific; DNA-binding transcription factor activity, RNA polymerase II-specific; RNA polymerase II transcription regulatory region sequence-specific DNA binding; DNA-binding transcription factor activity
Biological process: positive regulation of transcription by RNA polymerase II; regulation of cell population proliferation; regulation of DNA-templated transcription
Cellular component: chromatin; nucleus; transcription regulator complex
Genetic constraint (gnomAD): Loss-of-function variants: 9 observed, 40.34 expected, observed/expected ratio (o/e) 0.22, 90% interval 0.13 to 0.39. The upper end of that interval is the gene's LOEUF score, 0.39, which puts it in group 1 of 6, group 1 being the genes least tolerant of losing a copy. Missense variants: 498 observed, 559.53 expected, observed/expected ratio (o/e) 0.89, 90% interval 0.83 to 0.96. Synonymous variants: 248 observed, 232.2 expected, observed/expected ratio (o/e) 1.07, 90% interval 0.96 to 1.19.
Homologues: Orthologues: chimpanzee TFAP2D (100% identical), dog TFAP2D (100% identical), macaque TFAP2D (99% identical), guinea pig TFAP2D (99% identical), mouse Tfap2d (99% identical), pig TFAP2D (99% identical), rat Tfap2d (99% identical), rabbit TFAP2D (97% identical), tropical clawed frog tfap2d (93% identical), zebrafish tfap2d (88% identical), Drosophila melanogaster TfAP-2 (43% identical), Caenorhabditis elegans aptf-1 (27% identical), and 3 more. Paralogues in human: TFAP2B (52% identical), TFAP2A (51% identical), TFAP2E (48% identical), TFAP2C (47% identical).
Diseases named in the same sentence as TFAP2D in open-access papers:
TFAP2D is named in the same sentence as 13 diseases in open-access papers, as found by Europe PMC text mining. Sharing a sentence is not in itself a finding about the gene and the disease. The quoted sentences say what the papers report.
lung carcinoma (5 papers, 2022 to 2026). "Previous studies have noted the involvement of TFAP2D in prostate and lung cancer, suggesting broader relevance across malignancies." (PMID 41373739, 2025). "Lung cancer cell lines generally present the highest expression of TFAP2D, suggesting that research in this context should be pursued." (PMID 36552887, 2022). "Several articles on the role of TFAP2A/B/C in lung cancer progression have been published, but the role of TFAP2D/E in this process is still unknown." (PMID 39695171, 2024). "Background/Objectives: AP-2δ, encoded by TFAP2D, is one of the least characterized members of the AP-2 transcription factor family, although available evidence suggests biologically relevant roles in lung cancer that have not yet been thoroughly examined." (PMID 42073601, 2026). "Nonetheless, the TFAP2 genes family seems to play an important role in lung cancer pathogenesis, especially the TFAP2A, TFAP2C, and TFAP2D members in LUAD patients." (PMID 36831334, 2023).
lymph node metastasis (2 papers, 2020 to 2023). "TFAP2D staining was significantly linked to advanced tumor stage, high classical and quantitative Gleason grade, lymph node metastasis, and a positive surgical margin (p ≤ 0.0045)." (PMID 32143573, 2020). "TFAP2D staining was significantly associated with adverse tumor features, including advanced tumor stage, high Gleason grade, presence of lymph node metastasis (p < 0.0001 each) and a positive surgical margin (p = 0.0045)." (PMID 32143573, 2020).
prostate carcinoma (2 papers, 2020 to 2023). A carcinoma that arises from epithelial cells of the prostate gland. "Upregulation of TFAP2D parallels genomic instability in prostate cancer and is associated with adverse tumor features, rapid cell proliferation and poor patient prognosis." (PMID 32143573, 2020). "Therefore, a tissue microarray containing 17,747 prostate cancer specimens with associated pathological, clinical, and molecular data was analyzed by immunohistochemistry to assess the role of TFAP2D." (PMID 32143573, 2020). "That elevated TFAP2D expression was significantly associated with the majority of the analyzed deletions in ERG negative cancers highlights that elevated TFAP2D levels are either a cause or a consequence of genomic instability in prostate cancer cells." (PMID 32143573, 2020). "As cellular proliferation is dependent on the androgen receptor function in prostate cancer, it is possible, that the significant link between elevated Ki67 labeling index and high TFAP2D expression is also androgen receptor driven." (PMID 32143573, 2020). "The significant association of elevated TFAP2D expression levels with unfavorable prostate cancer phenotype and prognosis supports an in vivo role of TFAP2D in prostate cancer progression." (PMID 32143573, 2020). "For this purpose, TFAP2D protein expression was successfully analyzed in 13,545 of 17,747 prostate cancers that were available in a tissue microarray format." (PMID 32143573, 2020). "Nuclear TFAP2D staining was seen in 75.7% of 13,545 interpretable prostate cancers whereas adjacent normal prostatic epithelial cells were only occasionally TFAP2D positive." (PMID 32143573, 2020). "If TFAP2D expression analysis will have a role for prostate cancer prognosis assessment, this will most likely be in combination with other biomarkers." (PMID 32143573, 2020). "Based on the reported role of TFAP2D in prostate tissue and the implications of AP-2 family members in neoplasia, we aimed to determine the potential role of varying TFAP2D expression levels in prostate cancer." (PMID 32143573, 2020). "This suggests TFAP2D to be overexpressed during prostate cancer development." (PMID 32143573, 2020). "The results of our study demonstrate that nuclear TFAP2D protein expression is a predictor of poor prognosis in ERG negative prostate cancer." (PMID 32143573, 2020). "TFAP2D expression was typically increased in prostate cancer as compared to adjacent non-neoplastic glands." (PMID 32143573, 2020). "Positive TFAP2D immunostaining was significantly associated with 10 of 11 previously analyzed chromosomal deletions in ERG negative cancers (p ≤ 0.0244 each) indicating that elevated TFAP2D expression parallels genomic instability in prostate cancer." (PMID 32143573, 2020).
bipolar disorder (1 paper, 2025). A disorder of the brain that causes unusual shifts in mood, energy, activity levels and the ability to carry out day-to-day tasks. "Mutations in SOX4 and SOX11 cause intellectual disability and other neurodevelopmental alterations, and variants in the TFAP2D locus are associated with bipolar disorder and emotional dysregulation." (PMID 39814878, 2025).
bladder cancer (1 paper, 2023). "But in general, TFAP2E and TFAP2D has a better prognosis in bladder cancer." (PMID 37859819, 2023). "We used SMART database to analyze the methylation of different TFAP2 family in patients with BLCA, and found that the methylation of TFAP2A, TFAP2B, TFAP2D and TFAP2E in bladder cancer tissues was significantly higher than that in adjacent tissues, while TFAP2C showed the opposite trend." (PMID 37859819, 2023). "However, less study on TFAP2D and TFAP2E was carried out in bladder cancer, and its specific role and mechanism need further research." (PMID 37859819, 2023).
lung adenocarcinoma (1 paper, 2026). A carcinoma that arises from the lung and is characterized by the presence of malignant glandular epithelial cells. "The aim of the present study was to provide an integrated characterization of AP-2δ/TFAP2D in lung adenocarcinoma (LUAD) and lung squamous cell carcinoma (LUSC)." (PMID 42073601, 2026).
cancer (5 papers, 2020 to 2023). A tumor composed of atypical neoplastic, often pleomorphic cells that invade other tissues. "Nevertheless, the recent report has shown that TFAP2D mutational status may depend on changes in the expression of other cancer-specific genes and targets of FDA-approved drugs, which has been confirmed in data from LUAD patients." (PMID 36831334, 2023). "TFAP2D mutation may co-depend with changes in expression of both cancer hallmark genes and FDA-approved drug targets." (PMID 36552887, 2022). "Due to limited reports concerning the function of TFAP2D in cancer, we focused on describing the other four TFAP2 members." (PMID 37291585, 2023). "Among TcoFs, the most inquisitive appears to be TRIM22, which regulates all currently validated AP-2δ and its correlation with TFAP2D changes depending on tissue context (cancer vs. normal)." (PMID 36552887, 2022). "Additionally, research on TFAP2D is currently limited, and further studies are needed to extend our understanding of its role in cancers." (PMID 37291585, 2023). "High TFAP2D expression was strongly linked to TMPRSS2:ERG rearrangement and ERG expression: TFAP2D positivity increased from 66.5–73.5% in ERG negative cancers (by IHC or FISH) to 88.2–89.8% in ERG positive cancers (p < 0.0001 each)." (PMID 32143573, 2020). "Detectable TFAP2D expression was strongly linked to outcome in ERG negative cancers (p < 0.0001) but completely unrelated to patient outcome in ERG positive cancers (p = 0.9543)." (PMID 32143573, 2020). "This analysis revealed that the observed associations were largely caused by the subset of ERG negative cancers, while TFAP2D staining was unrelated to the analyzed features in ERG positive cancers." (PMID 32143573, 2020). "TFAP2D staining was considered weak in 73.4%, moderate in 2.3%, and strong in < 0.1% of cancers." (PMID 32143573, 2020). "TFAP2D expression was unrelated to patient outcome in ERG-positive cancers (p = 0.9453)." (PMID 32143573, 2020). "Compared with adjacent tissues, the expression of TFAP2A, TFAPB, TFAP2D and TFAP2E in cancer tissue was significantly increased." (PMID 37859819, 2023). "TFAP2D positivity was more common in ERG fusion positive (88.7%) than in ERG negative cancers (66.8%; p < 0.0001)." (PMID 32143573, 2020). "A further analysis based on subsets of all cancers with identical classical and quantitative Gleason grades revealed no significant prognostic impact of TFAP2D expression for any Gleason group." (PMID 32143573, 2020). "The increased frequency of TFAP2D positive cancers in ERG positive (90%) compared to ERG negative subsets (74%) suggests an interaction between ERG and TFAP2D, either directly or via modulation of shared common downstream targets." (PMID 32143573, 2020). "Subset analyses of ERG positive and ERG negative cancers revealed that the prognostic impact of TFAP2D expression was driven by the ERG-negative group (p < 0.0001)." (PMID 32143573, 2020). "TFAP2D staining was considered negative in 24.3% and positive in 75.7% of 13,545 interpretable cancers." (PMID 32143573, 2020). "For most tissues, the expression of TFAP2D gene was very low or there was none in most cancer types, and the differences between normal and cancer cells were not significant, although for LUAD and LUSC types the overexpression of this gene was found (p < 0.001)." (PMID 36831334, 2023). "Chromosomal deletions were generally more frequent in TFAP2D positive than negative cancers." (PMID 32143573, 2020). "An ERG specific cellular microenvironment may be responsible for the particularly prognostic role of TFAP2D-expression in ERG negative cancers or the mitigation of it in ERG negative cancers." (PMID 32143573, 2020). "Moreover, the complete lack of a tendency towards a different outcome between TFAP2D positive and negative cancers defined by a specific classical or quantitative Gleason grade demonstrates the power of traditional morphologic parameters if it comes to predicting patient outcome." (PMID 32143573, 2020).
cancer (continued). "The results of this analysis show that an independent prognostic role of TFAP2D measurement was limited to the pre-surgical scenario 4 in all cancers and ERG negative cancers (p = 0.0007 each)." (PMID 32143573, 2020). "Because of the strong link between increased TFAP2D levels and ERG rearrangement, the impact of TFAP2D expression on tumor phenotype and prognosis was separately analyzed in ERG fusion positive and negative cancers." (PMID 32143573, 2020). "Irrespective of the reason behind, the selective prognostic impact of TFAP2D in ERG negative cancers demonstrates that prognostic markers (or their defining thresholds) depend on other molecular tumor features and the intracellular microenvironment of cancer cells." (PMID 32143573, 2020).
tumor (4 papers, 2020 to 2025). "Tissue spots containing both normal and cancerous glands usually showed higher TFAP2D levels in the tumor cells than in normal glands." (PMID 32143573, 2020). "Other frequently correlated components included TFAP2B, TFAP2D, TFAP2E, TFAP2A-AS1, Meiothermus, and Corynebacterium, with the DLBC tumor cohort exhibiting the highest number of identified relationships." (PMID 41373739, 2025). "At present, the research on TFAP2D and TFAP2E in tumor is rare, compared to other genes in TFAP2 family." (PMID 37859819, 2023). "Scenario 3 included TFAP2D immunostaining, preoperative serum PSA, clinical tumor stage (cT) and the prostatectomy Gleason grade." (PMID 32143573, 2020). "The results for TFAP2D showed that expression of this gene was positively correlated with tumor purity, but only in LUSC (p = 0.0267), which means that in LUSC the gene expression is connected to the tumor cells." (PMID 36831334, 2023). "Our analysis of molecularly defined tumor subgroups revealed that the prognostic impact of TFAP2D expression was almost entirely driven by ERG negative cases." (PMID 32143573, 2020). "Gender, tumor grade, and TFAP2D may not be significantly correlated with tumor survival in the FFPE cohort." (PMID 37859819, 2023). "The analysis of TFAP2D gene in LUAD subtype revealed that significantly lower expression level was observed at stage 4 of LUAD vs. stage 1 (p < 0.001), stage 2 (p = 0.0063) and stage 3 (p = 0.0068), which may indicate inhibition of TFAP2D gene expression along with tumor development." (PMID 36831334, 2023).
TFAP2D also shares sentences with these, for which no sentence is quoted: calcinosis cutis (1 paper); depression (1); Intellectual disability (1); lung squamous cell carcinoma (1); neurodevelopmental disorder (1).